FNDC5 (fibronectin type III domain containing 5)
Diseases named in the same sentence as FNDC5 in open-access papers (continued):
Sharing a sentence is not in itself a finding about the gene and the disease.
lung carcinoma (6 papers, 2019 to 2024). "The mRNA levels of FNDC5 and ESRRA (encoding ERRα) were assessed in IMR-90 cells after co-culture with lung cancer cells." (PMID 36430689, 2022). "The effect of NCI-H1703 and NCI-H522 lung cancer cell lines on the FNDC5 mRNA expression levels in normal fibroblasts of the IMR-90 line was investigated." (PMID 36430689, 2022). "Normal fibroblasts, when incubated with cells of various lung cancer lines, showed a significant increase in the FNDC5 gene expression after only 24 h of incubation." (PMID 36430689, 2022). "We observed ultrastructural irisin/FNDC5 expression in the cytoplasm of lung cancer cells, in mitochondria and in the rough reticulum." (PMID 36430689, 2022). "The increased expression of FNDC5 in lung cancer cells blocked nuclear factor-κB (NF-κB) activation and downregulated the multidrug resistance protein 1 (MDR1) levels." (PMID 34071869, 2021). "Our in vitro study revealed a higher level of FNDC5 mRNA in cells of lung cancer lines NCI-1703 and NCI-H522 compared to the level in lung fibroblast cell line IMR-90." (PMID 31614634, 2019). "Importantly, FNDC5 expression is decreased in paclitaxel-resistant non-small-cell lung cancer, and exogenous irisin can increase the sensitivity of lung cancer to paclitaxel, thus contributing to treatment." (PMID 38143500, 2023). "In our previous study, we detected irisin/FNDC5 expression in the cytoplasm of lung cancer cells." (PMID 36430689, 2022). "However, the level of FNDC5 mRNA in IMR-90 cells after 72 h of co-culture with lung cancer cells of the NCI-H522 line was significantly lower than in control cells cultured with an empty insert (p = 0.0462)." (PMID 36430689, 2022). "The conducted experiment in an in vitro model indicated that the presence of lung cancer cells could induce an increase in the expression of the FNDC5 and ESRRA genes in stromal fibroblasts." (PMID 36430689, 2022). "Moreover, normal fibroblasts revealed the upregulation of the FNDC5 gene under the influence of lung cancer cells." (PMID 36430689, 2022). "Moreover, we noted the secretion of irisin/FNDC5 from lung cancer cells into the extracellular space." (PMID 36430689, 2022). "Furthermore, it was found that NSCLC cells that were resistant to paclitaxel, a chemotherapeutic agent used in the treatment of lung cancer, had decreased FNDC5 levels, and irisin treatment was able to attenuate this chemoresistance." (PMID 34071869, 2021). "Additionally, the results achieved by using LCM indicated that FNDC5 mRNA expression was noticed both in lung cancer cells (mean 1.4 ± 0.5) and in stromal cells (mean 1.7 ± 0.6) of NSCLC." (PMID 31614634, 2019). "We also performed a study showing the expression of irisin/FNDC5 in NCI-H522, NCI-1703 and A549 lung cancer cells using the immunogold technique." (PMID 36430689, 2022). "Changes in the expression level of the FNDC5 and ESRRA genes in fibroblasts simulating the lung tumor stroma after incubation with lung cancer cells have been described for the first time." (PMID 36430689, 2022). "Normal fibroblasts revealed an upregulation of the FNDC5 and ESRRA genes under the influence of lung cancer cells." (PMID 36430689, 2022). "In lung cancer, FNDC5 inhibits EMT and reduces the migration and invasion abilities of lung cancer cells by mediating the PI3K/AKT/Snail signaling pathway." (PMID 36386179, 2022). "One of the objectives was to verify whether the expression of FNDC5 and ESRRA genes increased in stromal cells due to the presence of lung cancer cells." (PMID 36430689, 2022). "However, there have been no in vitro studies to determine the impact of lung cancer cells on changes in the level of FNDC5 or ESRRA expression in lung fibroblasts." (PMID 36430689, 2022).
Myocardial fibrosis (6 papers, 2020 to 2025). "Our results showed that 8-week swimming intervention stimulated mRNA and protein expression of FNDC5 in myocardial tissues, which may be a major causative factor in ameliorating myocardial fibrosis in T2DM rats." (PMID 39250437, 2024). "Interestingly, FNDC5-MSCs significantly reduced myocardial fibrosis compared with the MI and MI + BM-MSC groups (p < 0.05)." (PMID 32522253, 2020). "A recent study demonstrated that resistance exercise also promotes FNDC5 expression, activates the AMPK-SIRT1 pathway, and inhibits myocardial fibrosis in mice with MI." (PMID 40182630, 2025).
Stroke (6 papers, 2017 to 2025). Sudden impairment of blood flow to a part of the brain due to occlusion or rupture of an artery to the brain. "Next, in stroke cynomolgus monkeys and rats, muscle atrophy, FNDC5/irisin/BDNF expression, and cognition were measured." (PMID 41201499, 2025). "Irisin/FNDC5 is a crucial regulator of the cognitive benefits of exercise in post‐stroke cognitive impairment." (PMID 40951931, 2025). "Important to this study, in a tMCAO rodent stroke model, irisin levels and skeletal muscle expression of FNDC5 were decreased in rats." (PMID 36062148, 2022). "Another protein of prognostic interest in post-stroke recovery is fibronectin type III domain-containing protein 5 (FNDC5), usually called irisin." (PMID 33920472, 2021). "The role of irisin and its precursor FNDC5 in stroke recovery with training is quite far to be fully elucidated." (PMID 28373915, 2017). "FNDC5 shows a significant number of pro-health properties, especially important for post-stroke patients, thus indicating that dysregulation in its concentration may constitute an ideal indicator for monitoring the improvement of health conditions in post-stroke patients." (PMID 33920472, 2021). "In cynomolgus monkeys, paretic muscle CSA fell by 40 % at 12 weeks post-stroke, along with a notable decrease in PGC-1α and FNDC5 protein in atrophic muscle." (PMID 41201499, 2025). "Post-stroke high-intensity interval training reduced ischemic brain damage and upregulated pTrkB (a major cascade of BDNF actions) and FNDC5 expression in the cortex of rats, which underscores its role in neuronal survival, hippocampal neurogenesis, synaptic plasticity, and functional recovery." (PMID 36062148, 2022). "This relationship irisin precursor, namely, FNDC5, and BDNF may be of fundamental importance in the comprehension of the role of training in stroke, particularly because physical exercise induces BDNF but also synapsin I in the hippocampal trisynaptic circuit." (PMID 28373915, 2017).
dementia (5 papers, 2018 to 2024). Loss of intellectual abilities interfering with an individual's social and occupational functions. "This review provides a comprehensive overview and updated analysis of the role and mechanisms of FNDC5/irisin in different forms of dementia and cognitive impairment." (PMID 38985081, 2024). "Decreased brain FNDC5/irisin has been reported in subjects with dementia due to Alzheimer’s disease." (PMID 37601408, 2023). "This could imply the involvement of FNDC5 in the prevention of AD, acting in the initial phases of the disease development when Aβ accumulation begins and before the onset of dementia." (PMID 33562601, 2021). "Considering the cascade of AD that Aβ accumulation may start about 20–30 years before the onset of dementia, FNDC5 may play an effective role in the preclinical stage." (PMID 30355327, 2018). "Moreover LIPUS-induced activation of hippocampal Fndc5/irisin signaling could be an alternative strategy to drive the benefits of exercise for dementia patients, especially the patients who are disabled." (PMID 36823656, 2023). "Thus, hippocampal Fndc5/irisin might be a critical molecular mechanism of dementia and potential to become a novel therapeutic target for dementia." (PMID 36823656, 2023). "Recently, studies involving the Fndc5/irisin signaling are booming in the dementia field, however, the role of Fndc5/irisin in VaD has not been investigated." (PMID 36823656, 2023).
nonalcoholic fatty liver disease (5 papers, 2018 to 2024). "Here, we investigated the involvement of fibronectin type III domain containing 5 (Fndc5) or irisin, which is a novel exercise-linked hormone, in the development and progression of nonalcoholic fatty liver disease (NAFLD)." (PMID 33754067, 2021). "In addition, patients with the presence of the FNDC5 rs3480 A>G gene variant have a low prevalence of fibrosis in nonalcoholic fatty liver disease (NAFLD)." (PMID 38143500, 2023). "In a mouse model of nonalcoholic fatty liver disease (NAFLD), SIRT2 regulated deacetylation and deubiquitylation of the fibronectin type III structural domain Fndc5, a process dependent on NAD+." (PMID 39852780, 2024).
gastric cancer (4 papers, 2021 to 2025). A primary or metastatic malignant neoplasm involving the stomach. "The association between FNDC5 and promoter methylation in gastric cancer patients was detected by UCSC Xena." (PMID 36386179, 2022). "Next, we analyzed the genes highly associated with FNDC5 in gastric cancer patients by WGCNA, and found that FNDC5-related genes were enriched in muscle system process, muscle contraction, and so on." (PMID 36386179, 2022). "However, survival analysis indicated that lower FNDC5 mRNA levels were associated with better overall survival and disease-free survival in gastric cancer patients." (PMID 36386179, 2022). "In a mouse model of gastric cancer-induced muscle cachexia, the expression of FNDC5 increased in adipose tissue, along with elevated levels of circulating irisin." (PMID 40869331, 2025). "Our experimental results suggest that FNDC5 inhibits the invasion and migration of gastric cancer cells." (PMID 36386179, 2022). "Then, we investigated the impact of FNDC5 in proliferation, migration and invasiveness of gastric cancer cells." (PMID 36386179, 2022). "The expression of FNDC5 and its value for the prognosis of gastric cancer patients were investigated." (PMID 36386179, 2022). "The role of FNDC5 in the regulation of gastric cancer cells proliferation, invasion, and migration was determined." (PMID 36386179, 2022). "We used multiple databases to carry out enrichment analysis of FNDC5-expressed genes and found that the expression level of KLF9 in gastric cancer patients was favorably correlated with FNDC5." (PMID 36386179, 2022). "Generally, these results suggest that TFs and DNA methylation modifications potential have an important effect on the occurrence and development of gastric cancer by regulating FNDC5 expression." (PMID 36386179, 2022). "Analysis of these datasets showed that the expression of FNDC5 was decreased in gastric cancer tissues compared with adjacent normal gastric tissues." (PMID 36386179, 2022). "Increased FNDC5 expression in white and brown adipose tissues of mice with experimentally induced gastric cancer may result from a cachectic effect." (PMID 40869331, 2025). "However, it confused us when Kaplan-Meier analysis showed that gastric cancer patients with high expression of FNDC5 had shorter overall survival than patients with low levels." (PMID 36386179, 2022). "The TCGA database was referenced simultaneously to determine whether FNDC5 levels were manipulated by modulating DNA methylation in gastric cancer." (PMID 36386179, 2022). "The expression analysis from gastric cancer-related GEO databases (GSE13195, GSE27342, GSE63089, and GSE65801) and TCGA database showed that the expression of FNDC5 was significantly downregulated in gastric cancer tissues compared with matched adjacent normal gastric tissues." (PMID 36386179, 2022). "However, the levels of FNDC5 mRNA were increased in white and brown adipose tissue in mice with experimentally induced gastric cancer (precancer group mice with glandular stomach/adenomatous hyperplasia, and cancer group mice with intramucosal and invasive cancer)." (PMID 34071869, 2021). "To investigate the impact of FNDC5 on gastric cancer cell proliferation, migration, and invasion, we transfected SNU-1 and AGS cells with HA-FNDC5." (PMID 36386179, 2022). "However, the role of FNDC5 in gastric cancer remains relatively unknown." (PMID 36386179, 2022). "Therefore, KLF9 may play a vital role in regulating the expression of FNDC5 in gastric cancer." (PMID 36386179, 2022). "Overexpressing FNDC5 inhibits the invasion and migration of gastric cancer but does not affect proliferation." (PMID 36386179, 2022). "We estimated the correlation of FNDC5 expression with 22 immune cells based on signature expression data from gastric cancer patients and found a significant negative correlation between FNDC5 and CD4+ memory-activated cells by using the CIBERSORT algorithm." (PMID 36386179, 2022).
gastric cancer (continued). "In vitro overexpression of FNDC5 inhibits the migration and invasion of gastric cancer cells, without affecting proliferation." (PMID 36386179, 2022). "Meanwhile, a significant negative correlation was found between FNDC5 and the abundance of CD4+ memory T cells in gastric cancer." (PMID 36386179, 2022).
ischemia (4 papers, 2020 to 2023). A hypoperfusion of the BLOOD through an organ or tissue caused by a PATHOLOGIC CONSTRICTION or obstruction of its BLOOD VESSELS, or an absence of BLOOD CIRCULATION. "FNDC5 and Irisin signaling induce repressing effects on mitochondrial dysfunction-mediated oxidative stress in ischemia/reperfusion-injured hepatic tissue, as well as protecting pulmonary tissue from the ischemia/reperfusion-induced loss of mitochondrial machinery and biogenesis." (PMID 32882839, 2020). "FNDC5/Irisin has also shown neuroprotective properties in conditions of ischemia." (PMID 33935687, 2021). "To investigate whether irisin plays a role in the protection of the heart from I/R, we induced 30min of ischemia followed by 24h of reperfusion in diabetic WT and FNDC5-/- mice, and then determined infarct size and cardiac function." (PMID 33013403, 2020).
liver cancer (4 papers, 2019 to 2023). An epithelial or non-epithelial malignant neoplasm that arises from the liver. "Studies have shown that the expression level of FNDC5 in liver cancer tissue is significantly higher than that of the normal control group, and FNDC5 can promote the proliferation of HCC cells and inhibit their apoptosis." (PMID 38021165, 2023). "Thus, the elucidation of the detailed molecular mechanistic roles played by GADD45β and FNDC5 in liver cancer will contribute to finding new therapeutic targets." (PMID 37746289, 2023). "The expression of FNDC5 mRNA was higher in liver cancer cells." (PMID 31614634, 2019). "With respect to liver cancer, high expression of FNDC1, FNDC3A, FNDC5, and FNDC7 was correlated with better prognosis, but increased expression of FNDC6 and FNDC8 was correlated with poor OS and PFS, respectively." (PMID 36626432, 2022).
steatosis (4 papers, 2020 to 2022). Increased lipid within the cytoplasm of cells. "The administration of recombinant FNDC5 repaired the attenuated autophagy in FNDC5−/− hepatocytes and in palmitate-induced steatosis, stimulating gene expression of targets related to autophagy and FAO." (PMID 33066678, 2020).
cardiomyopathy (3 papers, 2014 to 2022). A disease of the heart muscle or myocardium proper. "Our previous study has identified fibronectin type III domain‐containing 5 (FNDC5) and its cleaved form, irisin, as the cardioprotectant against doxorubicin‐induced cardiomyopathy." (PMID 35166002, 2022). "In the current study, we observed that Fndc5 deficiency at baseline elicited oxidative stress and apoptosis in H9C2 cells, imitating the phenotype of DOX-induced cardiomyopathy in vitro." (PMID 31209361, 2020).
Cerebral ischemia (3 papers, 2021 to 2025). Restriction of arterial blood supply to the brain associated with insufficient oxygenation to support the metabolic requirements of the tissue. "FNDC5/irisin as a novel therapeutic factor capable of improving cognition, learning, and memory function, which has been proved in brain injury caused in cerebral ischemia, stroke, and anxiety." (PMID 36225200, 2022). "FNDC5 expression in skeletal muscle and circulating Irisin levels were also decreased by cerebral ischemia." (PMID 33935687, 2021). "Besides, FNDC5/irisin-mediated microglial activation has been reported to be involved in cerebral ischemia and intracerebral hemorrhage, and it ameliorated neurological deficits, neuroinflammation, oxidative stress, and neuronal apoptosis." (PMID 40388874, 2025).
colorectal cancer (3 papers, 2018 to 2021). A primary or metastatic malignant neoplasm that affects the colon or rectum. "We here aim to comprehensively analyze the mRNA expression of FNDC1, FNDC3A, FNDC3B, FNDC4, FNDC5, and GPR116 in nonaffected and affected mucosal samples of patients with IBD or colorectal cancer (CRC)." (PMID 31093274, 2019).
Hyperinsulinemia (3 papers, 2018 to 2023). An increased concentration of insulin in the blood. "Overexpression of the fibronectin type III domain-containing protein 5 (FNDC5) gene, a precursor of irisin, resulted in adipose tissue browning, increase in oxygen consumption, amelioration of glucose tolerance and hyperinsulinemia, and reduction of obesity in mice." (PMID 29402279, 2018).
hyperlipemia (3 papers, 2019 to 2020). "Recent studies in our lab have shown that FNDC5 overexpression ameliorates hyperlipemia and enhances lipolysis in adipose tissues of mice, and prevents high fat diet (HFD)-induced hyperlipemia, hepatic lipid accumulation and impaired fatty acid oxidation in liver." (PMID 30940158, 2019).
muscle atrophy (3 papers, 2020 to 2025). The loss of muscle tissue due to inactivity or disease. "In this study, we investigated the alterations of FNDC5/irisin in GC-induced sarcopenia and evaluated whether irisin-based intervention could ameliorate GC-associated muscle atrophy and mitochondrial dysfunction." (PMID 41227321, 2025). "We noted intrathecal Ad-irisin attenuated pain sensitization and gastrocnemius muscle atrophy by modulating the level of irisin in CSF, and the expression of neuronal FNDC5/irisin and TNFα in the spinal cord." (PMID 33096842, 2020). "Given the observed downregulation of FNDC5/irisin in the Dex-induced muscle atrophy model, we investigated whether irisin reconstitution could rescue Dex-mediated myopathic phenotypes." (PMID 41227321, 2025).
myocardial ischemia (3 papers, 2020 to 2024). A disorder of cardiac function caused by insufficient blood flow to the muscle tissue of the heart. "Besides, FNDC5/irisin has been shown to inhibit ER stress to exert protective effects on some diseases, such as acute pancreatitis and myocardial ischemia/reperfusion injury." (PMID 38555440, 2024).
osteosarcoma (3 papers, 2021 to 2023). A usually aggressive malignant bone-forming mesenchymal neoplasm, predominantly affecting adolescents and young adults. "However, in the case of osteosarcoma, FNDC5/Ir inhibited STAT3 phosphorylation in the STAT3/SNAIL signaling pathway, which is also associated with the EMT process." (PMID 37239973, 2023). "FNDC5 was shown to inhibit EMT through the modulation of STAT3/Snail pathway in osteosarcoma." (PMID 36386179, 2022).
and Central Nervous System cancer (2 papers, 2023 to 2025). "Translational strategies for glioma include intranasal delivery to bypass the BBB and CRISPR-activation of FNDC5 (Irisin precursor) in muscle." (PMID 40370453, 2025).
Atrophy (2 papers, 2021 to 2022). Any weakening or degeneration, especially through lack of use. "In this study, we investigated the role of FNDC5/irisin in muscle atrophy caused by hypoxia in vivo and in vitro and identified that the decreased expression of FNDC5/irisin and the myogenic factors Mrf4 and MyoG may be important reasons in hypoxia-induced muscle atrophy." (PMID 35055073, 2022). "Therefore, activation of SIRT‐1 might be critical for FGF19 to attenuate PA‐induced muscle atrophy, metabolic disturbance and the decline in FNDC‐5/irisin expression." (PMID 33751819, 2021).